CD163 (CD163 molecule)
Diseases named in the same sentence as CD163 in open-access papers (continued):
Sharing a sentence is not in itself a finding about the gene and the disease.
sarcoma (22 papers, 2018 to 2025). A usually aggressive malignant neoplasm of the soft tissue or bone. "Immunohistochemistry of STS has shown that a diffuse distribution of CD163+ tumor-associated macrophages (TAMs) was prominent in all the human sarcomas tested in one study." (PMID 41375061, 2025). "This study demonstrated that the serum macrophage biomarkers CD163 and SIRP1α were adverse prognostic factors for the risk of relapse and overall survival in sarcoma patients." (PMID 36900335, 2023). "It was recently reported that CD163-positive macrophages are also associated with both proliferation in Saos-2 cells and tumor progression in a sarcoma-bearing mouse model by IL-6-induced STAT3 activation." (PMID 32256354, 2020). "Furthermore, tumors developed from sarcoma cells in CD163-deficient mice were smaller than those in wild-type mice." (PMID 32214052, 2020). "The association between CD68+CD163+ macrophages and metastasis-free survival highlights the complexity of macrophage biology, given that CD163+ macrophages have traditionally been associated with worse outcomes in many solid tumors, including various sarcoma subtypes." (PMID 40601026, 2025). "Furthermore, in sarcoma, soluble CD163 was associated metastatic disease and high-grade tumors." (PMID 39462379, 2024). "The presence of CD163-positive macrophages has been reported as a prognostic marker across various sarcoma subtypes, including leiomyosarcoma, myxoid liposarcoma, undifferentiated pleomorphic sarcoma, embryonal rhabdomyosarcoma, and synovial sarcoma." (PMID 40423041, 2025). "In sarcoma, Univariate analysis revealed that soluble CD163 was a significant prognostic indicator of overall survival." (PMID 39462379, 2024). "It has been shown that a high number of CD68+/CD163+ M2-like TAMs positively correlate with metastatic diseases at diagnosis and shorter survival in sarcoma patients." (PMID 38891109, 2024). "All these studies point towards an immunosuppressive effect of CD163 macrophages in sarcoma, as does the current study." (PMID 36900335, 2023). "Infiltrating CD163-positive macrophages outnumbered the tumour-infiltrating lymphocytes in all sarcoma types." (PMID 36900335, 2023). "Other markers, characteristic of sarcoma TAMs, are CD163 and CD68, specific for M2 and M1 macrophages, respectively." (PMID 37958467, 2023). "Increased levels of CD163+ TAMs correlated with decreased OS and higher histological grade in human sarcoma." (PMID 36686729, 2022). "Although there was similar density of CD68 (staining pan-macrophages) and CD163 (staining M2-polarized macrophages) in fibroblastic sarcoma, only high density of CD163 indicated higher tumor staging." (PMID 34257571, 2021). "UPS is known to have increased infiltration of CD68+ macrophages and CD163+ TAMs among the various subtypes of sarcoma." (PMID 33802565, 2021). "Abundant accumulation of CD68 and CD163-positive macrophages in sarcoma is also elucidated in a study involving 24 types of sarcoma including DFSP and MFS." (PMID 34257571, 2021). "CD163 promotes murine sarcoma progression by inducing IL-6 secretion, which indicates the pro-tumorigenic role of TAMs expressing CD163 in sarcoma." (PMID 32256354, 2020). "Histiocytic sarcoma cells are derived from bone marrow monocyte precursors, expresses monocyte-macrophage antigens (CD163, CD68, and lysozyme) and lack expression of myeloid antigens such as CD33, CD13 and MPO." (PMID 29463311, 2018). "Therefore, the panel felt that the diagnosis was LC sarcoma with aberrant expression of CD163, fitting with the current view of the histogenesis of “composite histiocytoses” from a histiocytic cell pool bearing the BRAFV600E or equivalent mutations and retaining some plasticity." (PMID 30084011, 2018). "We investigated the numbers of CD68-, CD163-, and CD204-positive macrophages in the intratumoral and marginal areas of sarcoma cases." (PMID 36690825, 2023).
sarcoma (continued). "Seventy-five sarcoma specimens (not limited to a single histological type), resected at our institution, were collected, and the number of CD68-, CD163-, and CD204-positive macrophages in the intratumoral and marginal areas was counted." (PMID 36690825, 2023). "Relationship between CD68, CD163 and CD33 density and patient characteristics of fibroblastic sarcomas." (PMID 34257571, 2021). "Correlation analysis revealed that the density of CD68, CD163 and CD33 was not only positively correlated with the total score of HMGB1, but also with the cytoplasm-staining score of HMGB1 in fibroblastic sarcomas." (PMID 34257571, 2021). "This study is the first to investigate soluble forms of the macrophage markers SIRPα, LILRB1, CD163, and CD206 in sarcoma, and its conclusions are in accordance with a large study conducted by Dancsok showing that SIRPα in tissue samples is an adverse prognostic factor for soft tissue sarcomas." (PMID 36900335, 2023). "Proliferation of human sarcoma cells is promoted in co-cultures with CD163-positive macrophages, but not with si-CD163." (PMID 35200587, 2022). "Intriguingly, unlike that observed for other tumours, the infiltration of M2-macrophages characterised either using CD163 gene or the Cibersort M2-Macrophage signature showed no significant prognostic correlation with any of the sarcoma subgroups investigated." (PMID 33207697, 2020). "A recent study revealed that CD163+ TAMs promoted expression of IL-6 and CXCL2 by cancer cells while inhibition of either IL-6 or CD163 macrophage-induced tumorigenesis in a co-culture in vitro system and a sarcoma mouse model." (PMID 32509781, 2020). "The second one (case 16) was thought by the submitter to represent a mixed LC/non-LC sarcoma since a subset of the infiltrate expressed LC markers, while other cells expressed CD163." (PMID 30084011, 2018). "TAMs may lead to immunosuppression in sarcomas through the expression of several markers, including PD-L1, CD80, CD206, CD163, and CSF1R; the release of cytokines including IL-1, IL-6, IL-8, IL-10, TNF-alpha, TGF-beta, and VEGF; and chemokines such as CCL2, CCL5, CCL18, and MMP-9." (PMID 38891109, 2024). "Furthermore, the expression of CD47 and SIRPA showed poor positive correlations with CD68+ and CD163+ macrophages in almost all sarcomas, except a solitary fibrous tumor, demonstrating a significant negative correlation between CD163+ and CD68+ TAMs, and CD47." (PMID 37958467, 2023). "In fibroblastic sarcomas, the total score and the cytoplasm-staining score of HMGB1 were positively correlated with CD68, CD163 and CD33 density, indicating that HMGB1 may act on M2-polarized TAMs and CD33-positive myeloid cells in fibroblastic sarcomas and contribute to disease progression." (PMID 34257571, 2021).
Stroke (21 papers, 2016 to 2025). Sudden impairment of blood flow to a part of the brain due to occlusion or rupture of an artery to the brain. "In the case of stroke, serum Sema7A levels have been associated with risk of morbidity, whereas serum CD163 has been reported to be negatively associated with prognosis." (PMID 38373967, 2024). "Once CD163 is expressed on the surface, the macrophage becomes implicated in a dynamic process of mediating inflammatory and oxidative conditions involved in stroke via serum Hb regulation." (PMID 33498620, 2021). "Peripheral blood ADAM17 activity and soluble CD163 levels were elevated in stroke patients relative to non-stroke control groups, and negatively associated with post-stroke lymphocyte counts." (PMID 29021532, 2017). "However, both Sema7A (OR, 2.017; 95% CI, 1.301–3.518; p = 0.005) and CD163 (OR, 2.283; 95% CI, 1.252–5.724; p = 0.03) were associated with the poor prognosis for stroke, after adjusting for stroke severity." (PMID 38373967, 2024). "Moreover, the percentage of CD163+/CD16+ events 24 h after IS was positively associated with stroke severity and disability." (PMID 37065487, 2023). "Collectively, these observations provide novel evidence that the innate immune system employs protective mechanisms aimed at mitigating the risk of post-stroke autoimmune complications driven by adaptive immune system overactivation, and that CD163 is key mediator of this phenomenon." (PMID 29021532, 2017). "In general, current studies on Sema7A/CD163 and stroke are mainly based on serum and arterial components." (PMID 38373967, 2024). "Our study discusses the relationship between Sema7A/CD163 and stroke etiology and prognosis based on thrombus samples." (PMID 38373967, 2024). "In this study, we investigated the relationship between Sema7A/CD163 expression in thrombi and stroke classification, along with other clinical characteristics." (PMID 38373967, 2024). "We compared the levels of Sema7A and CD163 between these groups and analyzed their relationships with stroke severity, hemorrhagic transformation and prognosis." (PMID 38373967, 2024). "In short, Sema7A/CD163 has potential as a prognostic marker for stroke, but more rigorous studies are still needed to validate the conclusions." (PMID 38373967, 2024). "Based on previous studies, we postulated that there are differences in Sema7A/CD163 expression between different stroke subtypes and prognosis." (PMID 38373967, 2024). "CD163 is an important efferocytosis-related biomarker of acute ischemic stroke and can help with stroke diagnosis and prognosis." (PMID 38992073, 2024). "A recent experiment using CD163 as a marker for rat BAMs revealed that the number of BAMs was increased within meninges, perivascular spaces, and ischemic parenchyma 3 days after stroke." (PMID 36644619, 2022). "The percentage of CD163+/CD16+ events 24 h after stroke was positively associated with NIHSS score and mRS at admission, suggesting that stroke severity and disability are relevant triggers for CD163+ expression in circulating CD16+ monocytes." (PMID 34201498, 2021). "Accordingly, elevated mRNA levels of CD163, probably in response to stroke-induced increases in circulating free hemoglobin, were found in the peripheral cells of ischemic patients." (PMID 34201498, 2021). "The modulatory nature of CD163 in the inflammatory cascade makes it a great candidate for studying the potential point of mediation in stroke damage." (PMID 33498620, 2021). "Microarray analysis showed increased expression of transcripts for Cd163 and Lcn2 (Lipocalin2) 1–5 days after experimental stroke in comparison to sham-operated controls." (PMID 29872438, 2018). "We detected VEGF expression surrounding blood vessels and in some CD163+ perivascular macrophages in the brain tissue of ischemic stroke patients deceased one day after stroke onset." (PMID 30092836, 2018).
Stroke (continued). "APX3330 treatment significantly promotes M2 macrophage polarization as indicated by decreased ED1 (M1 macrophage marker) and increased CD163 (M2 macrophage marker) in the IBZ of T1DM stroke rats (p<0.05, n=7/group)." (PMID 29896433, 2018). "D-4F treatment also significantly (n=8/group, *p<0.05) promotes M2 macrophage polarization which is identified by increased CD163 expression compared to PBS treated T1DM stroke rats at 48 hours after stroke." (PMID 29221142, 2017). "The primary objective of this work was to determine the role of CD163 within the context of stroke immunopathology." (PMID 29021532, 2017). "Collectively, our results demonstrate a novel role for CD163 as factor which mechanistically couples stroke induced-activation of the peripheral innate immune system and suppression of the peripheral adaptive immune system." (PMID 29021532, 2017). "The purpose of this study was to investigate CD163 as a possible effector of stroke-induced adaptive immune system suppression." (PMID 29021532, 2017). "The relationship between Sema7A/CD163 expression in thrombus components and stroke etiology and prognosis remains unclear." (PMID 38373967, 2024). "Starting from 5–6 days after a stroke in humans, CD163+ cells accumulate in the ischemic brain parenchyma, where they may also paradoxically acquire a pro-inflammatory phenotype, as also noted in other pathological contexts." (PMID 34201498, 2021). "Subsequent in vitro experiments suggested that this stroke-induced elevation in circulating soluble CD163 likely originates from activated monocytic cells, as serum from stroke patients stimulated ADAM17-dependant CD163 shedding from healthy donor-derived monocytes." (PMID 29021532, 2017). "Interestingly, we did not observe an effect of BML‐111 treatment on anti‐inflammatory cytokines IL‐10 and IL‐4 at 1 week post‐stroke, despite increased CD163+ microglia/macrophages." (PMID 28523230, 2017). "Additionally, a study of 378 subjects showed a negative association between CD163 in serum and stroke prognosis." (PMID 38373967, 2024). "Additionally, several biomarkers, most importantly CD163, may serve as potential biomarkers and therapeutic targets for acute ischemic stroke, aiding in stroke diagnosis and prognosis." (PMID 38992073, 2024). "While this study identified a clear role for sCD163 in stroke immunopathology in terms of its end-action, our experiments did not look to identify the soluble factors present in peripheral circulation following stroke which are responsible for triggering the shedding of CD163 from monocytes." (PMID 29021532, 2017). "Here, we report for the first time that 1 week of BML‐111 treatment increases CD163+ microglia/macrophage cell populations in the brain 1 week post‐stroke, indicating that BML‐111 may increase the M2c subpopulation as a mechanism of action to promote debris clearance and tissue remodeling." (PMID 28523230, 2017). "In addition to CD163, the markers identified in this study included several other genes that may be pathologically relevant within the context of the stroke-induced peripheral immune response." (PMID 29263821, 2016). "Ongoing work in our laboratory is aimed at characterising the relationship between peripheral-blood sCD163 levels and stroke-induced adaptive immune dysfunction, as CD163 may be therapeutically targetable as a means of rescuing adaptive immune responsiveness following stroke." (PMID 29263821, 2016). "Research shows a strong correlation between thrombosis, stroke prognosis, and inflammatory markers such as von Willebrand factor (VWF), CD147, CD163, C-reactive protein (CRP), neutrophil extracellular trap (NET), and Actin." (PMID 41036279, 2025). "An increased percentage of CD163+/CD16+ and CD163+/CD14++ events occurred 24 and 48 h after a stroke compared to the controls." (PMID 34201498, 2021).
Stroke (continued). "In stroke patients, peripheral blood ADAM17 activity and soluble CD163 levels are elevated, whereby CD163 can be shed from the plasma membrane via the metalloprotease ADAM17 to generate a soluble peptide with lympho-inhibitory properties." (PMID 34201498, 2021). "APX3330 promotes M2 macrophage polarization, marked by increased M2 macrophage marker CD163 and decreased M1 macrophage marker, ED1 expression in the IBZ of T1DM stroke rats." (PMID 29896433, 2018). "BML‐111 significantly increased the percent of Iba1+/CD163+ cells compared to the vehicle, indicating that BML‐111 increases the M2, anti‐inflammatory phenotype in microglia and macrophages 1 week post‐stroke (p < .001)." (PMID 28523230, 2017). "Considering the beneficial role of CD163+/CD16+ monocytes, our evidence suggests that stroke severity and disability may represent relevant triggers for the expression of CD163+ on circulating CD16+ subsets." (PMID 34201498, 2021). "Notably, a compound variable, indexing ADAM17 mRNA expression, CD163 mRNA expression, and cellular TACE activity was correlated with worse National Institute of Health Stroke Severity (NIHSS) scores." (PMID 33498620, 2021). "Thus, we detected a significant increase in the percentage of CD163+/CD16+ and CD163+/CD14++ events 24 and 48 h after stroke, compared to healthy individuals." (PMID 34201498, 2021). "RT-qPCR analysis of mRNA showed a trend for increased CD163 expression after experimental stroke although this was not statistically significant." (PMID 29872438, 2018). "We observed the expression of VEGF in the post-mortem human brain tissue of stroke patients deceased 24 h after stroke onset, and detected VEGF surrounding some brain vessels and CD163+ perivascular macrophages, suggesting that the findings in rats might be valid in acute ischemic stroke patients." (PMID 30092836, 2018). "CD163+ expression was more pronounced in CD16+ non-classical and intermediate monocytes, as compared to CD14+ classical subtype, 24 h after stroke." (PMID 34201498, 2021). "In a rat stroke model, although 1‐hour MCAO followed by 24 hours reperfusion did not significantly change the number of CD163+ BAMs, these BAMs upregulated the expression of leukocyte chemo‐attractants." (PMID 31749316, 2019). "The percentage of CD16+ cells expressing CD163 (median = 16.01%, IQR = 14.05–18.12) was higher (p < 0.01) than the percentage of CD14++ cells expressing this surface molecule (median = 12.46%, IQR = 11.88–14.63) 24 h after stroke, but not at a later time-point (i.e., 48 h after the insult)." (PMID 34201498, 2021).